ATM (ATM serine/threonine kinase)
Diseases named in the same sentence as ATM in open-access papers (continued):
Sharing a sentence is not in itself a finding about the gene and the disease.
tumor (continued). "We next packaged different serotypes of rAAV-ATM-EGFP/luciferase and rAAV-CB-EGFP/luciferase to detect the tumor specificity of the ATM promoter both in vitro and in vivo." (PMID 35615262, 2022). "Previous studies have shown that low expression of LCN2, ATM, and ATP1 increases the sensitivity of tumor cells to cisplatin." (PMID 36016575, 2022). "Although RYBP and apoptin were found to interact and exert selective tumor killing, overexpression of RYBP was shown to induce apoptin translocation back to cytosol; similar to the effect of ATM inhibition." (PMID 36233063, 2022). "IFNγ derived from CD8+ T cells activated by immunotherapy and ATM activated by radiotherapy synergistically inhibit SLC7A11, inducing ferroptosis in tumor cells." (PMID 36072803, 2022). "In line with previous observations, the four ATM PGVs identified in this study were found in women with ER + (/HER-) tumour characteristics, which is also the most common tumour type seen in LBC." (PMID 33763779, 2022). "Studies have clearly demonstrated that blocking ATM-related DDR can reverse T-cell senescence and suppressive TIME generated by Tregs and tumor cells, thereby enhancing anti-tumor immunity and immunotherapy." (PMID 36226174, 2022). "Analysis of myoCAF-rich TC-1 and MC38 tumors by IHC showed that ATM inhibition (fibroblast shRNA knockdown and AZD0156) resulted in a significant relocation of CD8 T cells from the tumor periphery to the tumor core." (PMID 36353752, 2022). "The genic deletion of ATM induced IFN response and enhanced lymphocyte infiltration into the tumor microenvironment via cGAS/STING activation." (PMID 35572596, 2022). "The genes BRCA2 (P=0.009),ATM (P=0.004), FANCA (P=0.001), andPARP1 (P=0.011) showed a lower expression in post-NACTresidual tumor samples (n=32) than in pre-NACT biopsy samples (n=98)." (PMID 35293552, 2022). "Increased cytotoxicity and anti-tumor activity were observed in cell lines and mice tumor models with defects in BRCA1/2, ATM, or other genes involved in DNA repair after treatment with olaparib, and this was linked with platinum responsiveness." (PMID 36077867, 2022). "Several other putative tumor suppressors in the chromosome 1p or 11q deletion regions including CHD5, UBE4B, CADM1, and ATM, have patterns that are similar to KIF1B, where a subset of samples exhibit strong ASE in the absence of deletions." (PMID 35246212, 2022). "Owing to their ability to trigger cell-cycle arrest and promote DNA repair through their downstream targets, ATM and ATR inhibitors are considered to improve clinical outcomes of tumor treatment in combination with radiotherapy." (PMID 36230796, 2022). "Together, these data suggest that ATM activation occurs in human tumors surviving treatment with EGFR inhibitors, where it likely plays a tumor protective role." (PMID 35353542, 2022). "In contrast, mice treated with the combination of ATM and EGFR inhibitors displayed sustained tumor regressions that lasted throughout the length of the study." (PMID 35353542, 2022). "Overexpression of LINC00312 combined with exposure to irradiation decreased levels of p-ATM, p-ATR, p-Chk1, and p-Chk2, which play a crucial role in DNA damage checkpoint control and tumor inhibition." (PMID 36294743, 2022). "Class M tumor profiles exhibit neoantigen-dependent CTL, whereas class C tumor profiles often indicate dependence on ATM." (PMID 36071479, 2022). "Knock down of ATM, AMPKα or the autophagy-regulatory proteins Beclin1 or ATG5 significantly reduced tumor cell killing." (PMID 36408163, 2022).
tumor (continued). "It is shown that the silencing of HMGB1 can inhibit the growth of transplanted tumor, and it does play a radio-sensitization effect in vivo, and its mechanism is related to the PI3K/AKT/ATM signaling pathway." (PMID 36260180, 2022). "According to previous findings, low expression of ATM, TAP1 and LCN2 will increase the sensitivity of tumor cells to cisplatin, which is the same as our study conclusion and further illustrates the accuracy of our method." (PMID 36016575, 2022). "When comparing expression levels of tumor and normal samples, expression of PRKDC, BRCA2, and ATM genes was higher in the tumors." (PMID 35054819, 2022). "Two germline PV/LPV were found in two patients, but were missed by tumor genotyping (one patient with BRCA1 large deletion and another patient with SNV in ATM)." (PMID 35326583, 2022). "If tumor genotyping only was performed, 96.1% (49/51) PV/LPV in HBOC genes would be detected while 2 germline HBOC PV/LPV would be missed (1 × BRCA1, 1 × ATM)." (PMID 35326583, 2022). "Two germline PV/LPV, found in two different patients (1.2% of 170), were missed by tumor genotyping (one patient with BRCA1 large deletion and another patient with SNV in ATM)." (PMID 35326583, 2022). "The cutoffs of ATM (0.3) and BRCA1 (1.0) expressions (tumor/non-tumor) were determined by receiver operating characteristic analysis." (PMID 34068585, 2021). "The pro-apoptotic tumor suppressor BIN1 inhibits the activities of the neoplastic transcription factor MYC, poly (ADP-ribose) polymerase-1 (PARP1), and ATM Ser/Thr kinase (ATM) by separate mechanisms." (PMID 34948122, 2021). "Here, the authors show that in response to DNA damage, ATM/ATR stabilize the centrosome clustering regulator KIFC1 leading to increased clustering efficiency and tumour recurrence." (PMID 33397932, 2021). "Synergy between 673A and ATM or ATR inhibitors was evaluated using the Chou-Talalay method and confirmed in vivo using cell line xenograft tumor studies." (PMID 33664846, 2021). "CHK1 and CHK2, which can be activated by ATM/ATR kinase, play an important role in DNA damage checkpoint control and tumor inhibition." (PMID 33431817, 2021). "CHK1 kinase is downstream of ATM/ATR kinase pathway and plays a crucial role in DNA damage checkpoint control and tumor suppression." (PMID 33669867, 2021). "Similar to ATM, ATR inhibition in murine models of MLL-rearranged AML can prevent tumor growth and also reduce the tumor burden." (PMID 34732266, 2021). "On the other hand, CRL5–WSB1 has been shown to promote tumor metastasis and promote cell cycle via degrading tumor suppressors VHL, RhoGDI2, ATM, etc.." (PMID 34164402, 2021). "Nevertheless, in patients with breast tumors, low expression of XRCC1, ATM, and BRCA1 correlates with high proliferation indexes, higher tumor grade, and the presence of dedifferentiated cells." (PMID 34930377, 2021). "First, it induces DDR to recognize and repair the damage through ATM/CHK2, leading to tumor suppression." (PMID 34732266, 2021). "Other examples from this study include well-described tumor-promoting genes such as SRSF2, DNMT3A, ATM, BRCA1 and PKM, for which Tax- and HBZ-alternative splicing events are now associated with ATLL for the first time." (PMID 34543356, 2021). "ATM also mediates phosphorylation and stabilization of Zinc finger e-box binding homeobox 1 (ZEB1) a transcription factor driving EMT, tumor invasion, metastasis, and therapy resistance." (PMID 34638302, 2021).
tumor (continued). "ATM is an apical kinase of the DDR pathway, which makes it an attractive anti-tumor therapeutic target." (PMID 34026622, 2021). "In contrast, mutant BRAF, ATM, LRP1B, FAT4, FMN2, TRRAP, and ROS1 had higher stromal score (except ATM), immune score and ESTIMATE score, and the tumor purity was lower than the wild-type." (PMID 33836681, 2021). "A report on the outcomes of 1211 men undergoing active surveillance, including 11 BRCA1, 11 BRCA2 and 5 ATM germline carriers, has shown that BRCA2 carriers are more likely to undergo a tumour grade re-classification in subsequent biopsies." (PMID 33106584, 2021). "Another route is through caspase-3/DNase-mediated accumulation of genome instability (e.g., DNA double-strand breaks) that trigger ATM-dependent activation of the transcription factors NF-κB and STAT3, known drivers of tumor growth." (PMID 32075223, 2020). "Interestingly, we also found the re-localization of large bright auto-phosphorylated ATM punctum foci from nuclei to cytoplasm in partially infected tumor cells, indicating that activated ATM may be involved in multiple cellular biological processes, such as selective pexophagy." (PMID 32479542, 2020). "In TOPARP-B, we treated 21 patients with suspected deleterious ATM aberrations: two achieved a RECIST or PSA response, and several others had circulating tumour cell count conversions following therapy." (PMID 31806540, 2020). "Overall, this work provided the first evidence of oncolytic NDV infection and membrane-fusion manipulation of ATM-dependent DSB signal activation to benefit virus replication and promote syncytia formation in tumor cells." (PMID 32479542, 2020). "Certain research reports described the role of miRNA-26a in ADEs to regulate several neurological diseases, including gliomas, in tumor microenvironments, by enhancing de novo tumor formation and radio-sensitivity through the “suppressor of PTEN and ATM”." (PMID 32957534, 2020). "The results of tumor analyses were confirmatory for PALB2 (5 ASTs in 5 tumor samples) and supportive for ATM (2 LOHs in 3 tumors), but the other genes contributed less (limited analyses)." (PMID 32566746, 2020). "We report for the first time that oncolytic NDV infection and F-HN co-expression triggers the activation of ATM-mediated DSB signals to promote viral replication and syncytium formation in tumor cells." (PMID 32479542, 2020). "Our results confirm that reduced ATM function, which can be partially determined by protein level, confers sensitivity to ATR inhibition in NB as it does in other tumour types." (PMID 32354033, 2020). "PARP inhibitors synergistically interact with ATM inhibitors by blocking firing of the replication fork and sensitizing tumor cells to PARP1 trapping, which leads to DNA damage and tumor cell death." (PMID 33324554, 2020). "The Mre11 complex and ATM govern a major axis of the DDR and several lines of evidence implicate that axis in tumor suppression." (PMID 32187176, 2020). "Her-2+ and PAM50.Her-2 subtypes were more common in tumours with low MYC mRNA and low ATM mRNA expressions (all adjusted p values ≤ 0.01)." (PMID 30746633, 2019). "This cellular reprogramming was characterized by an up-regulation of ATM, MLH1, MCL1 and MITF, genes known to be involved in DNA repair, cell survival and proliferation - essential pathways for tumor survival under stressful conditions like chemotherapy." (PMID 31597943, 2019).
tumor (continued). "In light of these results, we then performed a clonogenic assay to examine the anti-tumor effect of the combination of a conventional chemotherapeutical drug and the ATR or ATM inhibitor." (PMID 31805725, 2019). "The levels of ATM and γ-H2AX have been identified as biomarkers for radiosensitivity in various tumour cells." (PMID 30769804, 2019). "Direct targeting of the canonical pathways, e.g., by applying DNA-PKcs or ATM inhibitors, most likely hampers DSB repair in both normal and tumor cells." (PMID 30621219, 2019). "Based on the information above, we suppose the key molecule of DNA damage response (DDR), ATM not only contribute to cisplatin resistance but also play an important role in epithelial-mesenchymal transition (EMT) progress and tumor metastasis." (PMID 30961670, 2019). "Oncogene-induced replication stress serves as a tumour specific vulnerability and rationale for the clinical development of inhibitors targeting the DNA damage response (DDR) kinases (CHK1, ATR, ATM and WEE1)." (PMID 31500184, 2019). "However, since some encouraging studies suggest that ATM expression may serve as a prognostic factor in medical oncology, further investigation is still needed to relate the kinase activity of ATM with its expression level in both healthy and tumor cells." (PMID 31261657, 2019). "Whereas triple negative, Genefu subtype (ER−/Her-2−), PAM50.Basal were frequently expressing in tumours with high MYC mRNA and high ATM mRNA expressions (all adjusted p values ≤ 0.01)." (PMID 30746633, 2019). "ATM and ATR protect cells that are obtained from tumor progression by inducing cell cycle arrest and apoptosis in the early phases of tumorigenesis." (PMID 31772936, 2019). "Particularly ATM, PPP2CA, and HDACs are known to mediate the vulnerability of tumor cells towards irradiation and chemotherapeutic drugs." (PMID 31354846, 2019). "If ATM is additionally downregulated, the DSB repair machinery is inhibited, and cell death increased in tumor cells." (PMID 31354846, 2019). "Some studies have indicated that ATM expression is related to EMT and tumor metastasis in other tumor cells." (PMID 30961670, 2019). "Higher expression levels of stem/progenitor cell factors, such as Bmi1, 8-nitroguanine, DNA damage response (DDR) proteins (phosphorylated ATM and γ-H2AX), and manganese-SOD were higher in CD133+ tumor tissues than in CD133- tumor tissues." (PMID 31450710, 2019). "Nonetheless, the profound tumour regressions achieved in FaDu ATM KO xenografts show a clear combination benefit for DNA-PK and PARP inhibition in the ATM-null genetic background." (PMID 31699977, 2019). "Regarding tumor site, the DNA damage response genes, ATR, ATM and Chk1, showed a difference in their expression." (PMID 29870526, 2018). "Defects in ATM could also be compensated through the activity of ataxia telangiectasia And rad3-related protein (ATR), thus indicating potential synthetic lethality interactions between these pathways, as ATM mutated tumours would be vulnerable to ATR inhibition." (PMID 29329208, 2018). "Enrichment of pathways showed the interaction of these miRNAs with marked tumor suppression (PTEN, AXIN1, ATM, NLK), and important proto-oncogenes and tumor-promoting genes as MYC." (PMID 30201877, 2018). "After silencing ATAD3A, the expression of ATM, histone H2AX, and H3 was shown to decrease, inhibiting the DNA damage repair and ultimately promoting tumor cell radiosensitivity." (PMID 29688867, 2018). "Central to all these findings, we observed the downregulation of ATM and NLK genes, which represent important regulators in response to DNA damage in eBL tumor cells." (PMID 29132323, 2017).
tumor (continued). "To determine the in vivo efficacy of the novel ATM inhibitor (AZ31), we assessed treatment effects on tumor growth of eight unique CRC PDX models." (PMID 29340025, 2017). "ATM and DNA-PKc are two central constituents of DDR and their inhibition was shown to radiosensitize NSCLC cell lines as well as other tumor entities to photon irradiation under normoxia." (PMID 29287602, 2017). "Knock down of ATM, AMPKα or ULK-1 reduced the ability of [curcumin + sildenafil] to induce autophagosome formation and tumor cell death." (PMID 29245915, 2017). "In BR28, for example, relatively high frequencies of EGFR p.R521K and PTCH1 p.T1195S over ATM p.H1380Y, BRCA2 p.N289H, and BRCA2 p.N991D were observed in plasma compared to tumor tissue data, indicating tumor heterogeneity." (PMID 29156805, 2017). "Copy number analysis based on exome sequencing data using VarScan software showed that the genome area hosting ATM, BRCA2 and CCND2 genes had >2-fold intensity changes in all three paired tumor samples compared to matched normal tissue samples." (PMID 28423512, 2017). "Activated ATM leads to activation of transcription factors NF-κB and STAT3, known drivers of tumor growth." (PMID 28337983, 2017). "Of the DE miRNAs, there was a marked number targeting critical tumor suppressors (PTEN, AXIN1, ATM, NLK) and critical proto-oncogenes and tumor promoting genes such as MYC." (PMID 29132323, 2017). "To investigate the clinical significance of ATM expression in NSCLC, we measured ATM protein expression in resected tumours." (PMID 28418844, 2017). "In this regard, miR-101 can sensitize the tumor cells to radiation in vitro and in vivo by hindering both NHEJ repair and ATM-mediated signal transduction." (PMID 27973455, 2016). "Expression of the proliferation marker Ki-67 was also strongly reduced in the ATM knockdown tumours upon MEK treatment, whereas only a minor reduction was observed in control tumours." (PMID 27922010, 2016). "Increase in phospho-ATM levels was detected following CDV exposure and higher levels of γ-H2AX (a quantitative marker of double-strand breaks) were measured in tumor cells compared to normal cells." (PMID 27331622, 2016). "The S3 CRC tumor and matched normal data compared to the predicted model at ATM and HKR1 genes showed a greater agreement between the predicted model and the tumor than between predicted model and the normal data." (PMID 26735342, 2016). "A second encouraging result of combining ATM and PDGFRA inhibitors is that they not only reduce tumor cell proliferation, but also potently induce cell death." (PMID 26984279, 2016). "ATM is a central mediator of the DNA-damage response (DDR), which acts as a barrier against tumour progression." (PMID 26220524, 2015). "BRCA1 expression also differs by tumor microarray (BRCA1 elevated 2.16-fold, 4.38% FDR) along with alterations in the ATM/BRCA1 pathway using GSEA analysis." (PMID 25970777, 2015). "The ATM-ATR pathway, which plays a key role in the DNA damage response pathway, is frequently activated in tumor cells and was found to regulate NKG2D ligand via transcriptional regulation." (PMID 26439264, 2015). "The identification of ATM as a positive regulator of AKT activity strongly supports the idea that ATM may play a role downstream a panel of RTKs and more importantly that in certain contexts ATM may positively modulate cell survival and proliferation and tumor progression." (PMID 24681585, 2014).